PPARA (peroxisome proliferator activated receptor alpha)
Diseases named in the same sentence as PPARA in open-access papers (continued):
Sharing a sentence is not in itself a finding about the gene and the disease.
Obesity (continued). "Experiments conducted on obese mice showed that PPARα agonist treatments improved the obesity condition and glucose homeostasis in terms of glucose intolerance, insulin resistance, and hyperglycemia." (PMID 31683535, 2019). "On the other hand, obesity decreased the transcription of β-oxidation genes, such as PPARα, CPT1, and ACOX." (PMID 31246177, 2019). "Punicic acid, as a conjugated linolenic acid isomer, ameliorates glucose homeostasis and obesity inflammation through the activation of PPARα and PPAR-γ." (PMID 31089369, 2019). "When PPARα is overexpressed, it induces a change in the type of muscle fiber that protects mice from diet-induced obesity." (PMID 31336903, 2019). "While macrophages are known to regulate inflammation in obesity and diabetes and contribute to a pro-inflammatory status, they are pushed towards an anti-inflammatory phenotype by PPARα/γ agonism." (PMID 31725756, 2019). "Increased PPARα levels have been shown to increase liver fatty acid oxidation and reduce circulating triglyceride levels to regulate rodent obesity." (PMID 30034368, 2018). "UR exerts anti-inflammatory, anti-oxidative, anti-cancer, anti-obesity, and anti-diabetic activities by activating peroxisome proliferator-activated receptor alpha (PPAR-α) and 5′ AMP-activated protein kinase (AMPK) and increasing energy expenditure." (PMID 30423963, 2018). "PPARα agonists are reported to suppress obesity and obesity-induced abnormalities in glucose metabolism." (PMID 30041488, 2018). "This anti-inflammatory effect in the WAT suggests PPARα activation has the capacity to improve insulin resistance and ameliorate obesity." (PMID 30037087, 2018). "We also observed unique regulation of Pgc1b in the presence of CDDO-Im, which coactivates PPARA and contributes to enhanced β-oxidation and resistance to obesity." (PMID 29367259, 2018). "Oestrogen inhibits the actions of PPARα on obesity and lipid metabolism through its effects on the PPARα-dependent regulation of target genes." (PMID 29690611, 2018). "The development of PPARα/γ/δ pan agonists as anti-diabetic, anti-obesity, or hypolipidemic drugs is still actively ongoing." (PMID 30079233, 2018). "Peroxisome-proliferator-activated receptors (PPARs) are the nuclear hormone receptor including PPARα, PPARδ, and PPARγ, which play a critical role in regulation of obesity, cardiovascular diseases, and inflammation." (PMID 28293264, 2017). "In accordance with early-onset obesity is characterized in PPARα KO females, mice in groups FO(KO) and PO(KO) consistently had a greater body weight than the wild type during pregnancy." (PMID 28264465, 2017). "In conclusion, treatment with PTE inhibited lipid accumulation by inducing the expression of the master transcription factor PPARα, attenuated the low-grade chronic inflammation of obesity, and also altered gut microbiota profiles." (PMID 29056891, 2017). "This work demonstrated reductions in behavioral responses to peripheral inflammation after i.t. injection of a drug that reversed obesity-induced PPARα downregulation in spinal cord, even though the treatment did not affect metabolic parameters." (PMID 28871134, 2017). "The main mechanism of Ephedra sinica's ability to reduce obesity and hyperglycemia involves increasing peroxisome proliferator-activated receptor alpha (PPAR-α) and adiponectin activity and reducing tumor necrosis factor-alpha (TNF-α) activity." (PMID 29234439, 2017). "Indeed, PPARα deficient mice fed a HF diet exhibit an obese-phenotypic characterization whereas an activation of PPARα transcriptional activity leads to protections from adiposity and insulin resistance, which shows potential application for treatment of insulin resistance and obesity." (PMID 29075307, 2017). "PPARα decreases lipid levels, as its activation promotes fatty acids oxidation, and the use of PPARα agonists ameliorate obesity-related side effects." (PMID 28587101, 2017).
Obesity (continued). "We suggest that Creb/Crtc2 negatively regulates the Sirt1/Pparα/Fgf21 axis via the induction of miR-34a under diet-induced obesity and insulin-resistant conditions." (PMID 29192248, 2017). "In contrast, diet-induced insulin resistance was prevented in PPARα-/- mice despite the development of obesity." (PMID 27708683, 2016). "In another study, maternal HFD and obesity induces hypermethylation of Lep and hypomethylation of Pparα in the oocytes and in the liver of adult offspring." (PMID 26925174, 2016). "As pristanic acid could serve as an efficient agonist of PPARα, it is possible that an increased level of pristanic acid could result in decreased activity of PPARα, which in turn causes dysregulation of lipid metabolism and body weight, thereby contributing to obesity pathogenesis." (PMID 27434237, 2016). "Toll-like receptor 4- (TLR4-) mediated NF-κB activation in obesity severely impairs cold-induced type 2 immune responses, downregulates PPARγ and PPARα expression, and markedly reduces beige fat development." (PMID 28042289, 2016). "The phenotype of this PPARα KO includes hepatic steatosis and spontaneous, late-onset obesity, with sexual dimorphism." (PMID 27973445, 2016). "Mice with diet-induced obesity were treated with the PPARγ or PPARα agonist, pioglitazone or fenofibrate, respectively." (PMID 26770990, 2016). "Obesity-related changes in PPARα and PPARγ expression were highly tissue specific, with the expressions of both receptors significantly increased in the liver, yet profoundly attenuated in gWAT of obese mice when compared with matched NC-fed controls." (PMID 27439882, 2016). "This study is the first demonstration that supplementation of the diet with 8-HEPE can have a beneficial effect on various characteristics of obesity through the activation of PPARα." (PMID 27239345, 2016). "In this study, we aimed to investigate the hepatoprotective mechanisms of PPARα agonist WY-14643 in a genetic rat model of obesity." (PMID 26539534, 2015). "Others have shown that obesity-induced reduction of transcript of PPARα, which regulates β-oxidation, is prevented by quercetin supplementation." (PMID 26445592, 2015). "They showed that this juice component acted as a potent peroxisome proliferator-activated receptor-alpha (PPARα) activator to lower plasma and hepatic TG levels in an animal model of obesity." (PMID 25880734, 2015). "New generation drugs, such as PPARα/γ dual agonists, prevent the development of obesity and reduce the lipid accumulation in cardiac cells, even during a high-fat diet." (PMID 25158235, 2014). "The target genes regulated by PPARα and involved in lipid metabolism and obesity include CD36, LPL, ACC, ABCA1, CYP4a10, CYP4a14, UCP2, ACO and SCD1." (PMID 24705395, 2014). "Second, we applied a mathematical model to identify distinct mechanisms that contribute to changes in PPARα mRNA expression due to maternal obesity and HFD." (PMID 24416203, 2014). "PPARα-null mice develop obesity and high plasma triglyceride levels, and they are more vulnerable to high-fat diet-induced nonalcoholic fatty liver disease (NASH)." (PMID 25383754, 2014). "In this study, we examined molecular mechanisms that explain differential effects of a PPARα agonist (fenofibrate) and a PPARγ agonist (rosiglitazone) on macrophages during obesity-induced atherogenesis." (PMID 23620818, 2013). "The role of PPARα in inflammation has also been studied in the context of obesity-induced chronic low-grade inflammation, which is characterized by increased circulating inflammatory cytokines and acute-phase proteins." (PMID 23577023, 2013). "Collectively, these data suggest that cautions should be taken in considering activation of both LXR and PPARα as a strategy for treatment of obesity or obesity related diseases." (PMID 23762402, 2013).
Obesity (continued). "The focus of the current study is to assess the effects of concurrent activation of LXR and PPARα on systemic metabolism and hepatic fat accumulation under the status of obesity in which the metabolism of glucose and lipids are dysregulated." (PMID 23762402, 2013). "These genes are target genes of PPARs, which have essential roles in energy homeostasis and adipogenesis, and their expression is increased by the activation and elevation of PPARα and PPARδ, resulting in anti-obesity effects." (PMID 23382926, 2013). "In summary, in this study we demonstrate that combined treatment by activators of LXR and PPARα alleviated insulin resistance and improved glucose homeostasis but dramatically exacerbated hepatic steatosis in high fat diet-induced obesity." (PMID 23762402, 2013). "In conclusion, this study indicated that 13-oxo-ODA acts as an agonist for PPARα not only in vitro but also in vivo where it activated hepatic PPARα, resulting in suppresses of obesity-induced plasma and hepatic levels of TG." (PMID 22347463, 2012). "PPARα is known to have anti-obesity effects and is involved in the regulation of energy balance through fat catabolism." (PMID 23110176, 2012). "As PPARα is activated through direct binding to n-3 PUFA, liver PPARα function is compromised in obesity." (PMID 22675337, 2012). "In conclusion, our findings indicate that 13-oxo-ODA act as a potent PPARα agonist, suggesting a possibility to improve obesity-induced dyslipidemia and hepatic steatosis." (PMID 22347463, 2012). "Ligands for PPARγ are drugs for type 2 diabetes, and ligands for PPARα are also currently in clinical use for obesity." (PMID 22448168, 2012). "PPARα has previously been investigated in our study populations in relation to T2D- and obesity-related quantitative traits, but has also been suggested as a gene predisposing for NAFLD." (PMID 21339799, 2011). "Induction of obesity with high-fat diet in PPARα knockout or wild type mice suggested that PPARα protected against obesity-induced chronic inflammation in the liver." (PMID 21382489, 2011). "PPARα has been the subject of intense academic and pharmaceutical research because of its ability to improve obesity-related metabolic disorders." (PMID 20871824, 2010). "In OVX mice, E2 inhibited the actions of fenofibrate-activated PPARα on obesity, due in part to reductions in hepatic expression of PPARα-mediated FA β-oxidizing enzymes by E2, a process mediated through the inhibition of PPARα coactivator recruitment by E2." (PMID 20871824, 2010). "Thus, it is likely that PPARα functions on obesity may be enhanced in estrogen-deficient states." (PMID 20871824, 2010). "Many studies show that fenofibrate can modulate body weight in animal models of diabetes, obesity, and insulin resistance although another known PPARα stimulator perfluorooctanoic acid induces overweight at low doses in intact female mice." (PMID 20871824, 2010). "DEHP-treated mice were protected from diet-induced obesity via PPARα-dependent activation of hepatic fatty acid catabolism, whereas the activity of neither PPARβ nor PPARγ was affected." (PMID 20123618, 2010). "It is considered that such effects of phytol are valuable for the control of lipid abnormalities in common diseases including obesity, diabetes, and hyperlipidemia through PPARα activation in the liver." (PMID 20613991, 2010). "In contrast to males, fenofibrate slightly increased high fat diet-induced body weight and adipose tissue mass in female mice, suggesting a different PPARα action on females than on males in the control of obesity." (PMID 20871824, 2010). "For these reasons, PPARα is also considered to be an interesting target to study in relation to lipid metabolism and obesity." (PMID 20300479, 2010). "Both PPARα and ERs have similar structures, action mechanisms, and functions, suggesting the interaction of PPARα with ERs in the control of these metabolic diseases including obesity." (PMID 20871824, 2010).
Obesity (continued). "The focus of PPARα/RXRα has been mainly its role in obesity and atherosclerosis, however recent data suggests that crosstalk between PPARα and the estrogen receptors exists through competitive binding to the estrogen response elements." (PMID 20799942, 2010). "Altogether, these results demonstrate that DEHP protects from obesity by activating the catabolic functions of PPARα in the liver." (PMID 20123618, 2010). "We demonstrated that PPARα was required for the protective effect of DEHP by showing that both the protection from diet-induced obesity and the induction of oxidative genes in the liver were completely abolished in PPARα-null mice." (PMID 20123618, 2010). "In contrast, DEHP did not influence the body mass of PPARα-null mice, demonstrating that the anti-obesity action of DEHP requires PPARα only." (PMID 20123618, 2010). "Based on my published results showing the fenofibrate functions on obesity during various conditions, this paper will focus on the differential regulation of PPARα on obesity by sex differences and the interaction of PPARα and ERs in the regulation of obesity." (PMID 20871824, 2010). "The link with obesity andinflammation will be discussed separately for the three PPARisoforms: PPARα, PPARβ/δ, and PPARγ." (PMID 17389767, 2007). "In fact,PPARα expression increases in the liver during fasting and in several models of murine obesity.Chronic treatment of rodents with PPARα agonists such asfenofibrate or Wy 14643 increases hepatic UCP2 mRNAexpression." (PMID 17389766, 2007). "An anti-inflammatory role ofPPARα in the development of steatohepatitis is furthersupported by a study in which wild-type and PPARα −/−mice were fed a high-fat diet to induce obesity." (PMID 17389767, 2007). "This study provides a systematic four-week evaluation of potent and selective agonists of the three PPAR isoforms, the combinationof PPARα and δ agonists and PPARpan agonists in a single chronic model of diet-induced obesity." (PMID 17710237, 2007). "Therefore, PPARα in PT is expected to play a crucial role in systemic lipid metabolism against obesity and diabetes." (PMID 41460648, 2026). "We previously reported that global knockout of PTG produced dramatic upregulation of PGC1α/PPARα target genes that may be beneficial in obesity." (PMID 40454488, 2025). "miR-519d-3p is induced during adipogenesis and represses peroxisome proliferator-activated receptor alpha (PPARα) translation (with a key role in fatty acid homeostasis), suggesting that miR-519d may be involved in adipocyte hypertrophy in human obesity." (PMID 40725017, 2025). "The key bioactive constituents—pinocembrin (modulating PPARα pathway), galangin (exhibiting anti-obesity effects), and alpinetin (ameliorating oxidative stress) —could collectively influence lipid metabolism via PPAR signaling and gut microbiota modulation." (PMID 41011191, 2025). "Conversely, PPARα activation encourages the metabolism of fat for energy, which may mitigate the metabolic consequences of obesity." (PMID 40066031, 2025). "However, newer derivatives are being developed to act as dual agonists of both PPARα and PPARγ, offering potential benefits in treating conditions such as obesity and diabetic cardiomyopathy." (PMID 40732311, 2025). "Several molecular mechanisms have been identified that contribute to the increased cardiac fatty acid oxidation in the setting of obesity/T2D, with one of the most important being an increase in transcriptional activity of peroxisome proliferator-activated receptor-α (PPARα)." (PMID 40663803, 2025). "The crosstalk between ChREBPβ and PPARα in brown adipocytes might be of particular importance in the dysregulation of lipid metabolism in obesity." (PMID 40499650, 2025). "CAP could exhibit positive effects on lipid metabolism and prevent obesity through regulating the expressions of PPARα, SREBP-1 and FAS." (PMID 40972421, 2025).
Obesity (continued). "Furthermore, CYP2E1 interacts with the nuclear receptor PPARα to co-regulate obesity, and CYP2E1 gene knockout mice show significantly improved obesity and dyslipidemia under high-fat diets." (PMID 39859169, 2025). "Interestingly, PPARα has been identified as the primary PPAR subtype involved in the obesity-induced upregulation of ANGPTL4 expression in breast cancer cells." (PMID 40616161, 2025). "Consistent with this, our findings suggest that the PPARα signaling pathway may be involved in PEG400-mediated anti-obesity effects." (PMID 40004195, 2025). "In the current literature on the upstream activation proteins of AMPK and PPARα, it is well-established that adiponectin binds to adiponectin receptors AdipoR1 and AdipoR2 and exerts anti-lipid effects in obesity via activation of AMPK and PPARα pathways, respectively." (PMID 40176148, 2025). "However, this marked efficacy was accompanied with increased bile duct proliferation and increased inflammation, cautioning the safety of the combination of FGF19 and PPARα activation in the treatment of obesity and MASLD." (PMID 40815899, 2025). "Additionally, it can enhance lipid metabolism and insulin sensitivity through the SREBP-1c/PPARα signaling pathway, thereby preventing dietary obesity and related metabolic disorders." (PMID 38731261, 2024). "Another study was conducted on the hydroalcoholic extract of lemon balm (ALS-L1023) to examine its effect on the regulation of hepatic lipid accumulation, obesity, and insulin resistance and determine whether its mechanism of action involves PPARα." (PMID 38675115, 2024). "PPARα activation promotes FA oxidation and reduces TG synthesis, which helps alleviate obesity." (PMID 39202687, 2024). "Molecularly, DNA damage induces FAO via PPARα, which is suppressed by obesity‐mediated hypoxia." (PMID 38145969, 2024). "Interestingly, HFD-fed PPARα−/− (PPARα−/−/HFD) mice exhibited fasting hypoglycemia despite their obesity being comparable to that of HFD-fed WT (WT/HFD) mice." (PMID 38604598, 2024). "Research has shown that L. plantarum strains are effective in reducing obesity in mice by activating the PPARα/CPT1α pathway and decreasing the expression of SREBP-1 and tDGAT1 mRNA or by boosting the expression of genes related to bile secretion, such as cholesterol 7α-hydroxylase (Cyp7α1)." (PMID 38999741, 2024). "Finally, this work finds that improving FAO by PPARα activation ameliorates obesity‐driven chemoresistance and enhances the outcomes of chemotherapy in obese mice." (PMID 38145969, 2024). "According to the authors, ALS-L1023 may inhibit obesity and improve insulin sensitivity in part by inhibiting hepatic lipid accumulation via hepatic PPARα activation." (PMID 38675115, 2024). "In contrast, intestine-specific Pparα knockout mice are protected against obesity and NAFLD42." (PMID 37673856, 2023). "Interestingly, a previous study also showed that polyphenol-rich longan flower water extract had anti-obesity and hypolipidemic effects in rats fed a hypercaloric diet, upregulated PPARα gene expression, and decreased FAS gene expression." (PMID 36903329, 2023). "The reduced hepatic adiponectin signaling that activates the AMPK–PPARα pathway may also explain the attenuation of PPARα activity in obesity." (PMID 37286039, 2023). "These receptors have been recognized as a critical regulator of various cellular processes involved in the pathogenesisof diabetes, obesity, and related cardiovascular disorders.The PPAR gene family comprises three genes that encode four unique proteins: PPARα, PPARδ, PPARγ1, and PPARγ2." (PMID 37886153, 2023). "As such, polyphenols that are able to target UCP1 and PPARα, and increase their expression, thus inducing thermogenesis or stimulating fatty acid oxidation, have attracted considerable interest as novel strategies for the treatment of obesity." (PMID 36835279, 2023).